MTOR (mechanistic target of rapamycin kinase)
Diseases named in the same sentence as MTOR in open-access papers (continued):
Sharing a sentence is not in itself a finding about the gene and the disease.
tumor (continued). "A patient with a papillary tumor of the pineal region (CNS WHO grade 2; patient 25) and mTOR pathway activation in Phospho-IHC potentially due to allelic loss of PTEN and FGFR1 amplification was treated with everolimus with resulting SD until tumor progression after nine months." (PMID 35864412, 2022). "Also, ASIC1α can activate the PI3K/AKT/mTOR pathway and further mediate tumour cell resistance." (PMID 35840921, 2022). "Additionally, RNA-sequencing of RNF43659mut isogenic cells reveals decreased interferon response gene expression, that is reversed by PI3K/mTOR inhibition, suggesting that RNF43659mut may alter tumor immunity." (PMID 35676246, 2022). "However, the outcome of concomitant targeting of NOP56 and mTOR (shNOP56 plus rapamycin) was superior to that achieved by shNOP56 or rapamycin alone, leading to far more effective and potent suppression of xenograft tumor growth." (PMID 35039048, 2022). "Consequently, mTOR has become a new target in the field of tumor therapy." (PMID 36397350, 2022). "Therefore, the specific intervention of PDLIM5 expression may relieve the inhibitory effect of AMPK activation on mTOR under stress state, and then affect cell proliferation, accelerate cell apoptosis, and improve drug sensitivity of tumor cells to EGFR-TKIS." (PMID 34964410, 2022). "Due to a lack of events, primary tumor site, size ≥ 5 cm, Folpe’s and Bleeker’s risk categories and type of systemic treatment at diagnosis (none vs. chemotherapy vs. mTOR inhibitors) could not be tested." (PMID 34680376, 2021). "Similarly, the mTOR inhibitor everolimus did not demonstrate a survival benefit in patients with advanced GC in the GRANITE-1 study, likely in part because inhibition of mTOR activates a feedback loop which upregulates PI3K activity, thereby attenuating the anti-tumour efficacy of mTOR inhibitors." (PMID 33933113, 2021). "In addition, hyperinsulinemia mediates the production of IGF-1, inhibits the production of IGFBP in the liver, increases the bioavailability of IGF-1 and stimulates further tumor growth through excessive activation of the PI3K-Akt-mTOR pathway and Ras-MAPK pathway." (PMID 33842335, 2021). "Therefore, PD-L1 blockade therapy reduced mTOR activity and mTOR–mediated upregulation of glycolysis in tumor cells, which, in turn allowing more available glucose within the extracellular milieu of the tumor and restores TILs glycolytic capacity and, as a result, their effector function." (PMID 35250965, 2021). "Also, researchers found that tumor cell-intrinsic PD-1 may activate mTOR or Hippo signaling pathway, therefore facilitating tumor proliferation independent from immune system." (PMID 34326692, 2021). "Therefore, preventing the metabolic activity of tumor cells by modulating the PI3K/mTOR pathway may have the potential enormous to enhance glucose availability to T cells, thereby enhancing the antitumor activity of T cells." (PMID 35250965, 2021). "PI3K−Akt signaling pathway participates in the regulation of immune function: it has been shown that the downstream molecule mTOR could interact with T cells, B cells, NK cells, neutrophils, DC cells and other immune cells, and participate in the immune regulation of tumor development." (PMID 34040054, 2021). "Genes upregulated in both tumor and TAS of BA PCa patients as compared to WA included cell cycle markers CD19, CD2, CD53 and CD80, interferon response factor 8 (IRF8), phosphoinositide 3-kinase (PIK3CA), mechanistic target of rapamycin (mTOR), and metastasis-associated protein S100A4." (PMID 34316327, 2021).
tumor (continued). "A phase I clinical trial analyzing rapamycin effect on pediatric tumor panels, including OS, showed an anti-tumor activity, suggesting that the mTOR pathway can be targeted and could be combined with conventional chemotherapy to reduce or prevent the emergence of resistance." (PMID 33567616, 2021). "PRMT5 may act as a tumor-inducing agent in ESCC by modulating LKB1/AMPK/mTOR pathway signaling." (PMID 34124017, 2021). "DDIT4 is a stress-response protein whose main function is to inhibit mTOR under stressful conditions.DDIT4 is considered an oncogene, and its overexpression is significantly associated with poorer prognosis in tumor patients (Tirado-Hurtado, Fajardo & Pinto, 2018)." (PMID 34434660, 2021). "Thus, an inhibitor that targets both PI3K and mTOR may have superior anti-tumour activity compared to targeted mTOR alone." (PMID 34768941, 2021). "Importantly, the axis of mTORC2/acetylated FoxO/c-Myc expression confers an adverse prognostic impact to GBM patients, and it can be abrogated by dual PI3K/mTOR kinase inhibition, resulting in tumor cell death of xenograft tumor models using patient-derived GBM neurospheres." (PMID 33916219, 2021). "Aberrant mutations enable tumor cells to acquire this metabolic state, and the most studied aberrant mutations belong to the myelocytomatosis oncogene (MYC) and phosphoinositide 3-kinase (PI3K)–protein kinase B (Akt)–mammalian target of rapamycin (mTOR) signaling pathways." (PMID 34885023, 2021). "In addition, studies have shown that, affected by the higher glucose consumption rate of tumor cells, the mTOR activity of tumor infiltrating lymphocytes, the activation of T cell nuclear factor signals, and the ability of glycolysis are reduced, which leads to impaired antitumor effects." (PMID 33832428, 2021). "Additionally, western blotting showed that knocking down PRMT5 could dramatically upregulate the expression of LKB1 and the p-AMPK in tumor sections, while downregulating the expression of p-mTOR." (PMID 34124017, 2021). "Consequently, mTOR has become an effective target for some tumor therapies." (PMID 34732698, 2021). "In addition, using rapamycin to inhibit S6 phosphorylation, an mTOR downstream effector, can restore the PARPi sensitivity of resistant BC cells, and the combination of rapamycin and PARPi can obviously suppress BRCA1-deficient tumor growth in vivo." (PMID 33790792, 2021). "In accordance with this hypothesis, the PI3K/Akt/mTOR axis has been shown to be of the utmost importance in the capability of tumor cell to resist apoptosis induced by various therapies; this role is particularly well recognized in the context of gynecological malignancies." (PMID 33338300, 2021). "Growing evidence, in fact, has demonstrated that HIF and PI3K/Akt/mTOR pathways act in an integrated way, influencing each other and the common downstream signaling pathways, increasing gene expression, cell metabolism and survival, tumorigenesis, and tumor growth." (PMID 34199959, 2021). "Inhibitors of mTOR, for example, are currently being evaluated in the clinic, and the observation that floating cells are particularly sensitive is of interest, as we suggest it can be a potent inhibitor of metastasis if administered during the time window of cell detachment in a tumor." (PMID 34066490, 2021). "This study revealed the tumor-promoting effect of p62 in PTC by AKT/AMPK/mTOR pathway, contributing to the basic research on the occurrence and development of PTC, and further suggesting that p62 or p62 related molecule may be a diagnostic and therapeutic target for PTC." (PMID 33937040, 2021). "Therefore, mTOR inhibitors can be effective against both tumour growth and control of seizures." (PMID 34360713, 2021).
tumor (continued). "In addition, there is evidence that the sensitivity of tumor cells to therapeutic drugs could be restored by inhibiting PI3K/Akt/mTOR pathway, which also prompts the apoptosis of tumor cells." (PMID 35186896, 2021). "Moreover, PI3K/mTOR overactivation is the cause of relapse in a subtype of pediatric T-ALL; therefore, PKI-587, a dual specificity PI3K/mTOR inhibitor, can be used to inhibit T-ALL cell growth and delay tumor formation." (PMID 34732266, 2021). "Another reason for the low tumor-plasma concordance in our study may be the too low VAF of the mutations identified in tumors for some genes (e.g., MTOR, PIK3CA, ERBB3, and RAF1), raising the question of whether they are driver mutations or just passenger variants." (PMID 34356096, 2021). "Molecular alterations in RCC tumors have been extensively studied in the last decade, especially in ccRCC but neither identified mutations (e.g.,: VHL, BAP1, PBRM1, SETD2, KDM5C, MTOR) nor transcriptome-based ccRCC tumor sub-classification have straightforward clinical relevance." (PMID 33535553, 2021). "However, some recent studies showed that PD-1 could also be expressed in tumor cells and could activate mTOR (Mammalian Target of Rapamycin) or Hippo signaling pathway, therefore facilitating tumor proliferation independent of the immune system." (PMID 34326692, 2021). "Regarding potential mechanisms, leptin can activate the JAK2/STAT3, PI3K/Akt/mTOR, and extracellular regulated protein kinase (ERK) pathways by binding to its own receptors expressed in tumor cells and stromal components, including immune cells, endothelial cells and tumor-associated fibroblasts." (PMID 33842335, 2021). "If the tumor is already inoperable or shows borderline resectability, mTOR inhibitor treatment should be considered—after confirming immunohistochemical positivity for p70S6K—as this may provide a chance to perform resection after the shrinkage of the tumor." (PMID 34542724, 2021). "Interestingly, our results suggest that the mTOR signaling pathway may play an important role in the anti-tumor process of puerarin." (PMID 34863080, 2021). "The pharmacological treatments available to maintain FOXP3 expression, such as CPG methylation, histone deacetylase inhibitors and the mammalian target of rapamycin (mTOR) inhibitor rapamycin (sirolimus), can result in general immunosuppression, which could lead to tumour relapse and infection." (PMID 34919342, 2021). "Therefore, mTOR inhibition could be another important mechanism for PLORMT depletion-induced anti-tumor activity in NSCLC cells." (PMID 34326320, 2021). "Interestingly, decreased exosomal miR‐100‐5p in the tumour microenvironment could downregulate the activation of mTOR by the endogenous miR‐100‐5p." (PMID 34469038, 2021). "Hence, drugs inhibiting PI3K/Akt/mTOR are increasingly valued in tumour research." (PMID 34495871, 2021). "Since mTOR inhibition amplifies autophagy—a pro-survival mechanism —we hypothesized that adding autophagy inhibitors could enhance the anti-tumorigenic effect of the PI3K/Akt/mTOR pathway inhibitors in NEN tumor cells." (PMID 34944946, 2021). "Similarly, other systemic therapies, such as radiosensitizing chemotherapeutics, and mTOR inhibitors may also profit from combination with tumor-targeting radioconjugates." (PMID 33078260, 2021). "Thus, an in vitro coculture system was established to investigate whether macrophages in the tumor microenvironment affect the viability of tumor cells under γ-radiation during the pharmaceutical control of mTOR signaling." (PMID 33959512, 2021).
tumor (continued). "Additionally, Akt/mTOR pathway is often overactivated in human tumors resulting in tumor growth." (PMID 33490663, 2021). "Depending on the primary tumour location, histopathological features, and somatostatin receptor status, we have now a variety of treatment option including “cold” somatostatin analogues, mTOR inhibitors, and kinase inhibitors, as well as somatostatin-based radiotherapy." (PMID 33552155, 2021). "It was also reported that reduced editing of COPA was implicated in the pathogenesis of HCC and editing of COPAWT may switch it from a tumor-promoting gene to a tumor suppressor by deactivating the PI3K/AKT/mTOR pathway through downregulation of caveolin-1 (CAV1)." (PMID 33824874, 2021). "Thus, it is hypothesized that mTOR inhibitors may also have immunomodulatory functions in the tumor microenvironment." (PMID 33746989, 2021). "Thus, mTOR is a key protein in the pathogenesis of tumor growth in multiple organs." (PMID 33802643, 2021). "Other studies also call the attention to metabolism-targeting agents in combinations, which highlights that these could potentially enhance the impact of sensitizing strategies and accordingly, mTOR inhibitors could inhibit tumor progression as having a complex modifying role on metabolism." (PMID 34257622, 2021). "Thus, LCN2 may regulate different pathways, including cell cycle, MAPK, and mTOR proteins to promote tumor growth in IBC." (PMID 34342930, 2021). "However, activated mTOR phosphorylates S6K (ribosomal protein S6 kinase, p70S6K), which initiates a series of related cellular physiological responses including vascular and tumor cell proliferation and other pathways related to tumor formation." (PMID 33925400, 2021). "Therefore, the mTOR signaling pathway is a hot target in anti-tumor therapy research." (PMID 32175074, 2020). "However, whether mTOR cascade affects CCL2-mediated T cells chemotaxis in tumor remains to be further elucidated." (PMID 32483450, 2020). "In addition, utilizing the photosensitive nature of pan-mTOR inhibitors may provide a novel dual-mechanism for increasing the potency and efficacy against tumour growth and mTOR related disease states and indeed influencing other cellular functions of mTOR." (PMID 33142217, 2020). "Among the various molecular mechanisms reported so far, the mammalian target of rapamycin (mTOR) complex is described as a master regulator of local axonal translation and an important signaling process in axonal regeneration, while also being affected in many different tumor types." (PMID 32747606, 2020). "However, mTOR activation has been shown to occur in the only two studies investigating tumor-intrinsic PD-1 where PD-1 has a pro-tumor role, which may suggest that mTOR signal activation is necessary for PD-1 to exhibit tumorigenic activity." (PMID 33193345, 2020). "In tumor cells, aprepitant decreases p70 S6 kinase phosphorylation and attenuates the activation of the mTOR signaling axis, whereas SP activates mTOR and increases tumor cell growth and metastasis by activating p70 S6 kinase and the eukaryotic initiation factor 4E-binding protein 1 (4E-BP1)." (PMID 32962202, 2020). "However, besides somatic mutations, other biological mechanisms are involved in the upregulation of the mTOR pathway, as demonstrated by the reduced expression of tumor suppressors functioning in the mTOR axis and the clinical efficacy of agents targeting the pathway, such as everolimus." (PMID 32850899, 2020). "Thus, mTOR-inhibitors could be considered in these patients who suffer from continued tumor growth after irradiation." (PMID 31936793, 2020).
tumor (continued). "In addition to displaying alterations in the mTOR signalling pathway, subtype-1 tumours also display evidence of elevated ion channel and secretion pathway activities: a phenotype that is likely associated with increased trans-membrane transport of cell products." (PMID 31988390, 2020). "Therefore, we hypothesized that inhibition of the mTOR gene may inhibit the proliferation of tumor cells, induce apoptosis and induce G1 arrest in MCL." (PMID 32999755, 2020). "Moreover, UCHL1 can act as an mTOR inhibitor 45, and may protect tumor cells via activation of autophagy, which could offset PEM-induced apoptosis." (PMID 32483437, 2020). "However, at present there is little evidence that upregulation of mTOR in a resistance setting causes an mTOR-dependence and sensitizes resistant tumor cells to monotherapy with mTOR inhibitors." (PMID 32943635, 2020). "Therefore, diminishing the CCL2 and CCR2 interaction through the mTOR cascade may reduce TAMs recruitment and chemotaxis, subsequently promoting the anti-tumor effect of CD8+ T cells in TME." (PMID 32483450, 2020). "Emerging evidences suggest that the AKT/mTOR pathway can activate a series of processes involved in tumor initiation and progression, including cell proliferation, differentiation, survival, chemoresistance and metastasis, and therefore may be a potential target for anticancer therapy." (PMID 32655130, 2020). "Also, metabolic inhibitors such as metformin, which indirectly activates AMPK could suppress tumor growth via autophagy induction and mTOR inhibition." (PMID 32807122, 2020). "Due to hyperactivation of the PI3K/Akt/mTOR pathway could lead to aberrant cell growth and tumor invasion, thus investigated the mechanism of hyperactivation of this signaling pathway was the key to find new targets for tumor therapy." (PMID 33272245, 2020). "The chemotaxis-related mTOR cascade might be a potential target for anti-tumor immunotherapy." (PMID 32483450, 2020). "Moreover, increased CCL5 binding to CCR5 activates the protein kinase B/mechanistic target of rapamycin (AKT/mTOR) signaling pathway to promote tumor cell growth and invasion and induces the production of matrix metalloproteinase (MMPs) by macrophages to decrease adhesion and facilitate migration." (PMID 33178603, 2020). "Besides the biosynthesis of fatty acids, mTOR signaling was also hyper-activated, and pathways that included those of glycine, serine, and threonine metabolism reduce reactive oxygen species stress during tumor homeostasis." (PMID 33424926, 2020). "Therefore, we investigated whether FOXK1 exerts the tumor-promoting functions via Akt/mTOR signaling pathway." (PMID 32363163, 2020). "Consequently, adding SFN to an everolimus-based treatment may amplify its anti-tumor efficacy by inhibiting not only mTOR but HDAC, as well." (PMID 32512849, 2020). "Thus, blocking other tumor survival pathways such as PI3K/Akt/mTOR or Ras/MAPK may be required to overcome secondary resistance to AIs." (PMID 32099680, 2020). "Therefore, we hypothesized that the overexpressed SPARC M2 conditioned medium may reduce the activation of the AKT/ mTOR pathway in tumour cells, thereby attenuating the M2-mediated malignant tumour phenotype." (PMID 32226513, 2020). "In addition to AKT signaling, mTOR plays a crucial role in tumor proliferation and growth." (PMID 33293473, 2020). "However, mTOR expressions are slightly lower in tumor samples." (PMID 33311440, 2020). "Notably, increasing index I mainly positively correlated with the IC50 of drugs targeting kinases on oncogenic pathways, while index II predominantly sensitized tumor cells to drugs targeting the PI3K/mTOR pathway, kinases, chromosome modifications, and the cell cycle." (PMID 33194713, 2020).